TERT (telomerase reverse transcriptase)
Diseases named in the same sentence as TERT in open-access papers (continued):
Sharing a sentence is not in itself a finding about the gene and the disease.
tumor (continued). "In addition, the concurrence of BRAF mutations with TERT promoter mutations in CM is linked to a higher tumor aggressiveness." (PMID 36143375, 2022). "CM hepatocytes could be stably cultured for at least one month, can be transduced with lentiviruses to express tumor associated antigens as TERT, and can serve as a platform to generate immortalized cell lines." (PMID 35804458, 2022). "The mutation rate was 23.1% in patients with tumor size ≥5 cm and 43.2% in patients with tumor size <5 cm (p=0.0358), which may suggest that TERT promoter mutations were more likely to be detected in tumor tissues in the early stage." (PMID 35311090, 2022). "Moreover, TERT mutations are biomarkers of tumor aggressiveness and poor prognosis in several human cancer types." (PMID 36273184, 2022). "Similarly to HBV-related HCC, HCV-related cancers also show high TERT expression and telomerase activity which is associated with tumor progression and aggressiveness." (PMID 36358677, 2022). "In addition, treatment with Tert-ASO also inhibits the invasion and tumor progression of liver cancer caused by TERT activation." (PMID 36569303, 2022). "The presence of TERT promoter mutations showed a superior specificity for tumour clinical aggressiveness than the methylation of TERT promoter, as only 3.4% (2/58) against 10.9% (6/55) of disease‐free tumours were positive for TERT promoter mutations and promoter methylation, respectively." (PMID 35979662, 2022). "This mutation pair results in TERT activation that then triggers the telomerase to elongate telomere length and, as a consequence, leads to the immortal, anti-senescence, and proliferative properties of tumor cells." (PMID 34947936, 2021). "Since mutated TERT promoter regions within non-invasive urothelial lesions are not sufficient alone for the establishment of cancerous growth, this points to the contribution of other gene mutations as a requirement for tumor development." (PMID 33562516, 2021). "The results obtained in this pilot series, although not conclusive, are consistent with the hypothesis that the detection of early tumor markers, such as increased levels of circulating TERT mRNA, may be of help to assess the risk of cancer in SOT patients." (PMID 34746013, 2021). "However, we found no statistically significant concordance in any BRAF, KRAS, NRAS, and TERT promoter mutation between the tumor tissue versus plasma, and the metastatic lymph node versus plasma." (PMID 33915745, 2021). "Therefore, TERT mutation has been a crucial research hotspot in the pathogenesis of tumor since 2013 when it was firstly reported." (PMID 33938397, 2021). "Tumor subpopulation with TERT promoter mutation could have gradually expanded through repetitive recurrence, which enabled us to detect TERT promoter mutation." (PMID 33761111, 2021). "TERT mutations can be detected in different tumours including TC." (PMID 34923978, 2021). "Thus, TERT mutations appear to be the dominant cause of tumor progression among mutations in this cohort." (PMID 34778063, 2021). "Promoter mutations upstream of TERT may promote dysregulated telomerase activation in tumour cells but additional factors including epigenetic, transcriptional and posttranscriptional modifications also have a role to play." (PMID 33802026, 2021). "In particular, in PTC patients, coexisting BRAF V600E and TERT promoter mutations are associated with increased cancer aggressiveness, lymph node and distant metastases, and an advanced stage and increase tumor recurrence and mortality more rapidly than either alone." (PMID 34208345, 2021).
tumor (continued). "The presence of a TERT promoter mutation in the tumor could have important clinical consequences, including the correlation of mutation status of this gene and follow-up." (PMID 34071371, 2021). "Furthermore, frequencies of BRAF and TERT promoter mutations in the tumor tissues were also found to be in line with previous studies." (PMID 33915745, 2021). "Notably, patients with TERT promoter mutated tumours had a higher prevalence of the T/T genotype than patients with unmutated TERT promoter (p=0.0243)." (PMID 34858860, 2021). "In addition, higher TERT expression was associated with advancing tumor stage and cell differentiation and shorter TTP and OS after TACE." (PMID 33946181, 2021). "Therefore, it is conceivable that the -124 C>T TERT promoter mutation, inducing higher expression of TERT in the tumour, results in the increased severity of disease as we observed in our cohort of OCSCC patients." (PMID 34858860, 2021). "We found that TERT mutation is associated with neutrophil enrichment, indicating that this mutation may closely associated with tumor immunity." (PMID 33996815, 2021). "Direct promoter activation may also lead to increased TERT activity in tumor cells, and two common promoter mutations (-124 and -146 bp upstream of the TERT start site) are typically associated with increased telomerase activity." (PMID 34201898, 2021). "Our exploratory analysis revealed that, despite having similar tumor mutation burden, MBCs harboring TERT genetic alterations were significantly enriched for PIK3CA clonal mutations preferentially affecting hotspots (5/6, 83% TERT altered vs 5/38, 13% TERT WT; p = 0.001, Fisher’s exact test)." (PMID 33863915, 2021). "In line with previous reports, TERT promoter mutations in our series as a whole were associated with older age at diagnosis, more advanced tumor stage, more frequent need for a second treatment, and worse outcomes (around 67% of patient had persistent disease or died of their disease)." (PMID 33790328, 2021). "Importantly, the TERT promoter C228T mutation can convert normal bladder stem cells (NBSCs) into tumor-initiating cells." (PMID 34094968, 2021). "However, other studies in different tumour types have reported contradicting clinical effects of TERT promoter mutations, ranging from poorer survival associated with the -146 C>T TERT promoter mutation to unchanged clinical outcome." (PMID 34858860, 2021). "To meet this need we developed a two-component DNA vaccine based on the highly conserved core protein of HCV to target HCV-infected cells, and a renowned tumor-associated antigen telomerase reverse transcriptase (TERT) based on the rat TERT, to target malignant cells." (PMID 34067686, 2021). "However, it is also well established that the constitutive expression of TERT is strongly associated with carcinogenesis and TERT inhibition in cancer cells reduces tumour growth due to the induction of cell death." (PMID 34680452, 2021). "The interference of HCV core and TERT as DNA immunogens warrants further study, and calls for an alternative approach of sequential treatment of HCV by therapeutic immunization in combination with DAA, followed by therapeutic vaccination against tumor associated antigens, such as TERT." (PMID 34067686, 2021). "Moreover, this subject also presented with a TERT promoter mutation C228T in the bone specimen which is in accordance with the clinical picture of an aggressive tumor with local and distant metastases." (PMID 33716974, 2021). "Both the EML4-ALK gene fusion and the promoter TERT variant were confirmed in the primary tumor." (PMID 33878728, 2021). "To this end, we proposed that the TERT mutation may play essential roles in mediating IDH-related immune response in tumor microenvironment (TME)." (PMID 33996815, 2021).
tumor (continued). "Male patients with HCV and/or alcoholic related cirrhosis have a higher prevalence of TERT promoter mutations both in tumor tissue and in cfDNA, providing the rationale for TERT promoter mutations analysis in cfDNA for early detection in some populations at risk of developing HCC." (PMID 34068786, 2021). "Indeed, while patients with the -124 C>T TERT promoter mutation had a higher risk of mucosal failure and poorer DFS and OS, patients with tumours harbouring the -146 C>T mutation had an improved clinical outcome, similar to those with unmutated TERT promoter." (PMID 34858860, 2021). "The presence of the C250T mutation in 2XSB cells led us to ask whether TERT mRNA was highly expressed in 2XSB cells and the parent tumor compared to wild-type Schwann cells." (PMID 33707600, 2021). "However, in contrast to MIBC polyclonal TERT mutations within the same bladder specimens were identified in tumor associated normal urothelium and non-invasive urothelial lesions." (PMID 33562516, 2021). "The TERT gene encodes a telomerase reverse transcriptase catalytic subunit and assembles into a ribonucleoprotein protease complex to maintain telomere length which plays an important role in the maintenance of tumor genome stability." (PMID 34094968, 2021). "Six patients shared single EGFR hotspot mutations (L858R in five and 19Del in one), and one patient shares an other/rare mutation (TERT Amplification); each tumor also harbored an abundance of unique mutations, ranging from four to 28 mutations per tumor, with no shared additional mutations." (PMID 34109114, 2021). "TERT promoter mutations could induce TERT transcription or telomerase activation, and promote tumor initiation and progression." (PMID 33297335, 2020). "The next step is to confirm whether TERT mutation is an immune predictive marker for a specific tumor or certain types of tumors through prospective or retrospective studies." (PMID 32810393, 2020). "Various previous researches provided a rational explanation that the levels of epidermal growth factor receptor amplification and interleukin 6 could be upregulated by TERT promoter mutations, inducing tumor angiogenesis and necrosis." (PMID 32509858, 2020). "Our results support the hypothesis that a mutation in the TERT promoter is sufficient for the inactivation of the gene in somatic cells, triggering replicative senescence as a tumor suppressor mechanism." (PMID 33257697, 2020). "In the benign lesions TERT mRNA positive tumours were associated with the presence of lymphocytic infiltrate (p < 0.0001), 85% of the FTAs (11 cases) with positive TERT mRNA expression had lymphocytic infiltrate vs. 15% (2 cases) negative for the presence of lymphocytic infiltrate." (PMID 32659948, 2020). "Strikingly, TERT mutation could be frequent in many malignancies and be identified as biomarkers of tumor aggressiveness and poor prognosis in several human cancer types." (PMID 32915164, 2020). "Interestingly, in one other tumor both the TERT C228T variant and two DICER1 variants were found (E1813D and a stop-gain variant Q1230 * predicted to result in nonsense-mediated decay)." (PMID 32455687, 2020). "Tumor necrosis seems to be closely related to TERT promoter mutations." (PMID 32509858, 2020). "The high percentage of TERT promoter mutations in HCC/iCCA may reflect the presence of the HCC part consisting of the TERT promoter mutation or indicate that both tumor types may arise from the same cell type of origin." (PMID 32722302, 2020). "TERT promoter mutation in HNSCC samples according to tumor sub-sites." (PMID 32850388, 2020). "Several investigators have shown that TERT promoter mutations are significantly more common among older patients, bigger tumor size, more aggressive subtype, tumors with extrathyroidal invasion, distant metastasis or higher stage at diagnosis, and are related to poor outcomes." (PMID 32751594, 2020).
tumor (continued). "In addition, TERT promoter mutations were identified in all the patients with GBM that had driver mutations in tumor-free SVZ tissue." (PMID 33330101, 2020). "As for other tumor types, we need to determine whether male patients with TERT mutations benefit from immunotherapy." (PMID 32915164, 2020). "The BRAFV600E mutation acts synergistically with TERT promoter mutations and the presence of both mutations is associated with greater cancer aggressiveness, lymph node and distant metastasis, advanced tumor stage, recurrence, and increased mortality in patients with PTC." (PMID 32849278, 2020). "Our findings indicated that TERT promoter mutations were more likely to be present in male patients, and those of older age, with larger tumor size, and strongly-associated vascular invasion, extrathyroidal extension, LNM, distant metastasis, and advanced TNM stage in PTC." (PMID 31655978, 2020). "Moreover, TERT mutations are identified as biomarkers of tumor aggressiveness and poor prognosis in several human cancer types." (PMID 32915164, 2020). "The facilitation of cell division by the TERT promoter mutation may lead cancerous cells to divide more quickly, divide, the more cell death and tumor lysis occur, which might increase releasing of tumor antigen." (PMID 32957941, 2020). "Additionally, the list includes studies that analyzed TERT promoter mutations in different tumor entities." (PMID 32722302, 2020). "Somatic mutations in ATRX, DAXX, or TERT were found in 16% of tumor samples." (PMID 32024817, 2020). "In the remaining six cases, TERT mutations matched with the mutations in other tumor components." (PMID 32213857, 2020). "However, structural rearrangements were also reported to trigger the extreme up-regulation of TERT and be associated with tumor aggressiveness." (PMID 31235699, 2019). "The inevitable question whether these eight FT-UMPs with TERT promoter mutations in fact were misclassified FTCs subjected to poor tumor sampling prompted us to re-investigate these specimens from a histological perspective." (PMID 31561592, 2019). "Notably, only tumor cell explants with a BRAFV600E-mutated background harboring loss of CDKN2A expression in combination with TERT promoter mutation developed into stable, immortalized cell lines." (PMID 31391125, 2019). "Therefore, TERT promoter mutations confer the tumor with a selective advantage, and are recurrently observed in human cancers, often in cases with dismal outcomes." (PMID 31561592, 2019). "To determine whether the TERT promoter also harbored a variant in our system, we performed targeted Sanger sequencing on DNA from each of the tumor samples." (PMID 31217899, 2019). "Differently from the vast majority of cancer driver mutations that fall within the coding region of oncogenes and/or tumor suppressors altering the resulting proteins, TERT promoter mutations occur within non-coding elements, and their mechanism of action has only partially been elucidated." (PMID 31200515, 2019). "Since aberrant expression of TERT is associated with tumor development, HBV and/or L1 sequence insertions in the proximity of the TERT locus may have a role in carcinogenesis by affecting the TERT expression." (PMID 30717368, 2019). "This could indicate that only a subclone of the tumour contains TERT promoter mutations, or that false low VAFs due to technical issues caused by GC rich gene regions makes detection of this variant difficult in plasma." (PMID 31767937, 2019). "Interestingly, TERT promoter mutations in tumor-free SVZ tissue were identified in all patients with IDH-wild-type GBM with driver mutations." (PMID 31482066, 2019). "At multivariate analysis, high levels of TERT in tumor were significantly associated with a higher risk of regional failure (HR = 5.75, 95% CI: 1.16–28.49; P = 0.032), increased risk of progression (HR:2.12,; 95% CI: 1.00–4.47; P = 0.049) and death (HR:3.53, 95% CI: 1.47–8.52; P = 0.005)." (PMID 31772219, 2019).
tumor (continued). "Similarly, TERT promoter mutation was associated with aggressive thyroid tumor characteristics, tumor recurrence, and patient mortality." (PMID 31300059, 2019). "Experiments based on TERT overexpression (either WT or mutant variants) have to be taken with caution since the levels obtained are generally much more important than those observed in tumor cells." (PMID 31911897, 2019). "Patients with GBM present mutations in the TERT promoter in the tumor-free SVZ." (PMID 31482066, 2019). "Interestingly, the single patient harboring a tumor with additional TERT promoter mutation showed the most aggressive course of disease." (PMID 31391125, 2019). "Indeed, these drugs seem to hamper tumor spreading by different sides and having beneficial effects both in tumor harboring TERT promoter mutations and in the wild type ones." (PMID 31200515, 2019). "Specific mutations within the TERT promoter, C250T (−146C > T), C228T (−124C > T) and A161C (−57A > C), have been identified to play an important role in telomerase re-activation in multiple tumor types including HGG." (PMID 31391125, 2019). "As a result, mutations in the TERT promoter were found in 21 out of 41 tumor samples (51.2%)." (PMID 29693015, 2018). "In a similar fashion, the prevalence of telomerase activity is higher than the prevalence of TERT promoter mutations in this tumor type, suggesting that these tumors may use TERT promoter-independent mechanisms for the reactivation of telomerase." (PMID 29616301, 2018). "We identified one of the hotspot 5′ UTR mutations in TERT in a VHL patient’s tumor." (PMID 29656891, 2018). "Interestingly, we also found that triple-positive tumor located more superficial to cortex than TERT mutation only tumor." (PMID 28915860, 2017). "A couple of studies have confirmed that the prevalence of TERT promoter mutations in tall cell variant PTCs, is also much higher than the CPTC cases, and TERT promoter mutation might predict highly significant tumor relapse in tall cell variant PTCs." (PMID 28423545, 2017). "In order to verify the hypothesis that TERT promoter mutation was correlated with telomere-dependent activity in NCCHCCs, we quantified the telomerase activities in tumor tissues by TRAP (telomeric repeat amplification protocol) assay." (PMID 28460432, 2017). "Combining these with previously identified TERT promoter mutations, most of the somatic mutations in the driver genes were in higher allele frequencies than the background mutations (χ2-test, P-value <1E−6) and were shared among all tumour sectors." (PMID 28240289, 2017). "In the dysplastic cell line POE9n tert, the observed pattern of CNAs is indicative of p16 (CDKN2A) inactivation and telomerase (TERT) activation; results of the assay are therefore consistent with an oncogenic pathway implicated in cellular immortalization and tumor progression." (PMID 28928368, 2017). "Interestingly, higher expression level of cytoplasmic TERT was significantly associated with lower level of α-fetoprotein and tumor well-differentiation (P = 0.028 and P = 0.021, respectively, Mann-Whitney test)." (PMID 28460432, 2017). "Human Telomerase (TERT) has been identified as a common hallmark of cancer, since it plays a critical role in aberrant cell proliferation and immortalization in the majority of tumours." (PMID 29152058, 2017). "Comparing pre-treatment and autopsy specimens, we demonstrated a common core of four early genetic events (loss of chr10, chr9p21, gain of chr7 and TERT promoter mutations), occurring before the divergence of primary tumor and post-treatment tumor, which are detectable in virtually every case." (PMID 29872714, 2017). "However, TERT promoter mutations occur in up to 50% of HCCs and the mutation frequency varies significantly with tumor types." (PMID 28416747, 2017).